RNU6-401P (RNA, U6 small nuclear 401, pseudogene)
Gene: Small nuclear RNA gene on chromosome 15 (83,717,427 to 83,717,522, forward strand). Ensembl gene ENSG00000212374.
Homologues: Orthologues: chimpanzee U6 (99% identical), macaque U6 (78% identical), dog U6 (74% identical), pig U6 (69% identical), mouse Gm55875 (67% identical), mouse Gm23641 (65% identical). Paralogues in human: RNU6-38P (88% identical), RNU6-996P (86% identical), RNU6-1011P (85% identical), RNU6-1029P (85% identical), RNU6-1056P (85% identical), RNU6-1062P (85% identical), RNU6-1124P (85% identical), RNU6-1237P (85% identical), RNU6-1249P (85% identical), RNU6-12P (85% identical), RNU6-13P (85% identical), RNU6-16P (85% identical), and 1287 more.